RAC1 (Rac family small GTPase 1)
Diseases named in the same sentence as RAC1 in open-access papers (continued):
Sharing a sentence is not in itself a finding about the gene and the disease.
melanoma (continued). "However, both RHO GTPase arms cross-talk with pro-survival/proliferation signalling, given that RHOA-ROCK were shown to cooperate with pro-survival mediators (such as STAT3 and NF-κB in melanoma cells) while RAC1 activated PI3K-AKT in breast cancer cells." (PMID 35159327, 2022). "One possible mechanism may be the suppression of the de-differentiated state, as SRC and RAC1 maintained markers of de-differentiation in human melanoma cells." (PMID 36271142, 2022). "We then investigated whether the role of circZNF609 in the metastasis of melanomas was dependent on RAC1 modulation." (PMID 35534866, 2022). "Therefore, we have chosen MMP2, MMP9, Pyk2, and Cyclin D1 as tumor metastasis indicators to explore the mechanism of how PCDH9 and RAC1 act on melanoma." (PMID 36387162, 2022). "To this end, we first evaluated the expression levels of RAC1 in melanoma cohorts." (PMID 35534866, 2022). "Indeed, RNA sequencing, ribosomal profiling, and iCLIP sequencing suggested that CSDE1 regulated pro-metastatic factor RNA regulons and mediated invasion and metastasis by regulating translation elongation of vimentin and Rac1 mRNA in melanoma." (PMID 35490208, 2022). "This knowledge is important as targeting the RAC1-pathway may sensitize an intrinsically therapy-resistant subtype of melanoma to BRAFi." (PMID 36271142, 2022). "Besides, CSDE1 was also verified to have tumor-promoting effects in melanoma by regulating the translation of vimentin and Rac-1." (PMID 35923244, 2022). "Although the alteration of PCDH9 could influence CCND1 but not the cell cycle, which suggested it may affect melanoma cells by other mechanisms, such as SOCE combined melanoma cell migration, RAC1-dependent NADPH oxidase correlated with GTP-GDP switch." (PMID 36452505, 2022). "Interestingly, melanomas dependent on TEAD1 tended to also depend on RAC1 according to Depmap CRISPR dependency scores." (PMID 36271142, 2022). "PI3K -RAC1 activation regulates EMT in melanoma cells and promotes metastasis." (PMID 34827551, 2021). "Altogether this suggests that targeting RAC1-mediated signaling could be of value in specific melanoma cases." (PMID 34503171, 2021). "RAC1 regulation of invadopodia in melanoma is controversial." (PMID 34827551, 2021). "In addition, a common activating mutation of RAC1 has recently been discovered in melanoma, and RAC1B, a constitutively active splice-variant of RAC1, is observed in colon cancer." (PMID 33397922, 2021). "Regarding MMP expression, there is a study that relates MMP-2 to RAC1 in melanoma cells." (PMID 34827551, 2021). "In addition, NX-5 has the potential to have similar inhibitory effects as Cdc42 inhibitor, Rac1 inhibitor, and RhoA inhibitor in human melanoma cell lines." (PMID 34201921, 2021). "Indeed, genetic alterations involving Rac1 have been identified in a variable proportion of melanomas and lung, uterine, and breast cancers." (PMID 34943902, 2021). "Additionally, NX-5 (20 μM) treatment significantly decreased the mRNA and protein expression levels of Cdc42, Rac1, and RhoA in melanoma cells compared with the untreated group (p < 0.001 and p < 0.05, respectively)." (PMID 34201921, 2021). "Several prominent genes mutated in CSD melanomas included NF1, ROS1, GNA11, and RAC1." (PMID 34680367, 2021). "Collectively, all these observations are intriguing, since it is known that Rab5-dependent macropinocytosis and cytoskeleton remodeling via Rac1 activation are critical events in tumor cell migration, as shown in HeLa, A375m2 melanoma and BE colon carcinoma cells." (PMID 33339852, 2020). "We demonstrated that RAC1-driven mechanisms of resistance to MAPKi could be prevented through Src inhibition, providing new options for future targeted therapies in melanoma." (PMID 32346533, 2020). "Dong Wei identified that ATF2, SOX2, and RAC1 are involved in the metastasis of melanoma." (PMID 33336008, 2020).
melanoma (continued). "The Rac1 GEF, DOCK1, is a potential therapeutic target for macropinocytosis in tumours with Rac1P29S mutation, as its inhibition caused a decrease in invasion and macropinocytosis of both melanoma and breast cancer cells harbouring Rac1P29S mutations." (PMID 32057095, 2020). "In melanoma, the elongated/mesenchymal phenotype of cells is driven by activated Rac1." (PMID 33202906, 2020). "Most notably, our 3D approach showed that invasive melanoma cells are featured by high plasticity, with cells capable of modulating either RhoA or Rac1 small GTPases and thus adopting two alternative modes of invasion: amoeboid (rounded) or mesenchymal (elongated), respectively." (PMID 33202906, 2020). "Finally, we showed for the first time that 1A-116 inhibits Rac1P29S, a rapid-cycling mutant of Rac1 that is frequently found in melanoma and other tumor types." (PMID 32351958, 2020). "The activation of RAC1 depends on the levels of ROS and determines the ability of the migration and invasion of B16 melanoma cells which could be weakened by the suppression of ROS-mediated Rac-1 activation." (PMID 31636809, 2019). "Likewise, elevation of NEDD9 expression was detected in 30 to 50% of metastatic melanomas samples and promoted mesenchymal migration of melanoma cells through activation of RAC1 and inhibition of RHO/ROCK-driven amoeboid movement." (PMID 30642390, 2019). "Currently, work is being done to develop specific Rac1 inhibitors for the treatment of melanoma." (PMID 30791562, 2019). "Thus, we can exclude an essential role of Rac1 in the regulation of invasive migration of BRAFi‐R melanoma cells." (PMID 30582770, 2019). "Next, we investigated whether combined inhibition of both IL‐6 and WNT5A signalling had any effect on Cdc42‐GTPase or Rac1‐GTPase activity in BRAFi‐R melanoma cells." (PMID 30582770, 2019). "Our results highlighted the importance of RAC1, SOD2, and SOD3 variants in the risk of melanoma." (PMID 29342889, 2018). "Studies of melanomas have shown that Rac1/P29S is found in about 5% to 9% of all melanomas." (PMID 30544828, 2018). "RAC1, a newly defined melanoma oncogene, is shown to enhance NOX1 activity." (PMID 29342889, 2018). "We suggest that these results shall be further validated with the goal of designing novel screening targets to identify highly UV-susceptible individuals, particularly in the RAC1 and SOD2 genes, in order to take the melanoma primary prevention strategy to a precision level." (PMID 29342889, 2018). "Therefore, we conjecture that the decrease of Rac1 expression promotes high degree of microtubule recombination in melanoma cells, and further promotes the migration and invasion ability of melanoma cells." (PMID 28404912, 2017). "Similarly, membrane rafts govern the participation of the small GTPase Rac1 in regulation of HSP expression in B16F10 melanoma cells." (PMID 29142280, 2017). "While promoting activity of RhoA, IQGAP1 may also decrease activity of Rac1 in the cell tail during melanoma migration, which may require interactions with C-terminal domains of IQGAP1." (PMID 29240845, 2017). "We also observed that WISP-1 inhibited phosphorylation of RhoA/Rac1/CDC42 in C8161 melanoma cells." (PMID 27813493, 2016). "Constant Rac1 activation has been observed in multiple tumor cell lines including melanoma cell." (PMID 26202910, 2015).
melanoma (continued). "To establish whether Rac1 might mediate SPARC effects on melanoma cell plasticity, we made use of a constitutively active Rac1 mutant (RacQL) and a dominant negative Rac1 mutant (RacDN) to modulate Rac1 activity." (PMID 26248315, 2015). "In the context of melanoma, somatic splice-site mutation of TMEM216 suggests potential tumor suppressor function and sets the RHOA/GNA12 pathway apart from the Gs-protein/MAPK pathway by mutual exclusivity of TMEM216 towards known oncogenes NRAS and RAC1." (PMID 25600636, 2015). "Interestingly, mutant B-Raf regulates a shift to N-cadherin and enhanced invasiveness of melanoma cells through the downregulation of Rac1 activity." (PMID 26248315, 2015). "By using a multidisciplinary approach, we identified four different treatments able to induce MAT in melanoma cells: EphA2 overexpression, Rac1 functional inhibition using its RacN17 dominant negative mutant, stimulation with Ilomastat or treatment with the RhoA activator Calpeptin." (PMID 24690323, 2014). "This pathway is also embroiled in invasion by regulating expression and activity of factors, such as RAC1, involved in cell motility and in degradation of basal laminae components, such as the metalloproteases MMP-9, allowing melanoma cells to invade the underlying dermis." (PMID 24416617, 2013). "Rac1 inhibition, using pharmacological or genetic approaches, was reported to impair melanoma tumor growth and spreading to distant organs in the Tyr::NRas (Q61K) mouse model, suggesting a potential value for RAC1 as a therapeutic target, at least in some context." (PMID 24416617, 2013). "In conclusion, the present study may provide a novel method through which narrow-band UVB radiation may be used to promote dendrite formation by activating the Rac1 signaling pathway, resulting in F-actin rearrangement in B16 melanoma cells." (PMID 24649261, 2013). "Therefore, in addition to HNSCC, RAC1 amplification in melanoma (representing 6–22% cases of metastatic melanoma) may also be targetable, in principle, by Rac inhibitors." (PMID 39941730, 2025). "A recent study has suggested that increased Rac1 activity may be one consequence of disruptions of the PTEN tumor suppressor pathway in melanoma, raising the possibility that PTEN-deficient melanomas may represent another potential context for beneficial co-targeting of BRAF/MEK and FAK." (PMID 41109929, 2025). "Therefore, we currently favor the hypothesis that expression of constitutively active Rac1 can promote a FAK-dependent cellular phenotype in certain melanoma cells." (PMID 41109929, 2025). "Since Src kinases collaborate with focal adhesion kinase (FAK) to signal towards cell survival and proliferation, we hypothesized that FAK inhibitors (FAKi), which continue to be clinically investigated, might also show utility against Rac1-driven drug-resistant melanoma cells." (PMID 41109929, 2025). "Extending our findings to other cancers, we also provided evidence that A159V mutation in endometrial cancer and RAC1-amp in melanoma (but not P29S melanoma hotspot mutation) may also be potentially druggable with Rac inhibitors." (PMID 39941730, 2025). "In addition, the obtained data suggest that the key molecules RAC1, RAS, and BRAF, which are frequently mutated in human melanoma, may also contain activating mutations in ghM, whilst PTEN may harbor loss-of-function mutations." (PMID 40724880, 2025). "Among them, the high expression of RAC1 was associated with a shorter survival time of melanoma patients, and whether RAC1 could influence the behavior of melanoma cells has not been studied before." (PMID 37217516, 2023). "Hence, RAC1 is a good indicator to reflect the effect of PCDH9 on melanoma." (PMID 36452505, 2022).
melanoma (continued). "Bioinformatics technologies have been applied to screen genes that may be relevant to the Chinese population, and the results indicated that PCDH9 was closely related to the prognosis of patients with MM, whereas RAC1 always played the opposite role in our natural bioproduct against melanoma study." (PMID 36387162, 2022). "Rac1 usually does not mutate, except in certain cancers, such as melanoma." (PMID 34079763, 2021). "Therefore, it may be valuable to evaluate clinically RAC1 mutational signature as a predictive biomarker for MEK/RAF inhibitor and anti-PD-1 and PD-L1 therapy resistance in melanoma patients." (PMID 34827551, 2021). "In contrast, the CSD melanomas had a higher frequency of mutations than the nevogenic melanomas in NF1 (14/37, 37.8% vs. 6/82, 7.3%; p < 0.001), ROS1 (10/37, 27.0% vs. 4/82, 4.9%; p = 0.001), GNA11 (4/37, 10.8% vs. 1/82, 1.2%; p = 0.032), and RAC1 (6/37, 16.2% vs. 1/82, 1.2%; p = 0.004)." (PMID 34680367, 2021). "RAC1 P29S confers resistance to BRAF inhibitors through the SRF/MRTF signaling pathway, indicating that targeted SRF/MRTF therapy may overcome BRAF inhibitor resistance in melanoma patients with RAC1P29S mutations." (PMID 34804979, 2021). "Indeed, constitutively active mutant of RAC1 (RAC1P29S) is found in 10% of MAPKi progression melanoma tumors and overexpression of PAK may promote MAPKi resistance in some settings." (PMID 32346533, 2020). "Taken together, we argue that a pharmacological intervention with RAC1 inhibitor (or its downstream effectors) in combination with anti-PD-L1/PD-1 antibody may provide a novel therapeutic opportunity in BRAF inhibitor-resistant melanoma patients." (PMID 32545340, 2020). "Beyond the 4% of melanoma cases with mutant RAC1, it is also worth speculating whether RAC signaling pathways may be activated in melanoma and perhaps other tumor types by different mechanisms, such as alterations in upstream regulatory proteins such as PREX and TIAM1." (PMID 31257073, 2019). "The RhoA/Rac1 ratio in the presence of aODN and aODN + inhibitor cocktail conformed to the classical amoeboid pattern indicating a prevalence of RhoA activity in prostate cancer cell lines, while it showed smaller variations with respect to controls in melanoma cell lines." (PMID 24681666, 2014). "Indeed, we could show that WNT5A induced activation of Cdc42 also in malignant melanoma Mewo cells and introduction of DN-Cdc42 and -Rac1 inhibited the WNT5A induced release." (PMID 24766647, 2014). "RAC1 is a RAS-related GTPase that regulates cell proliferation and migration; RAC1P29S is a recurrent UV-signature mutation in cutaneous non-acral melanomas and was the third most frequent activating mutation (9.2%) after those of BRAF and NRAS in a large cohort (n=147) of exome-sequenced melanomas." (PMID 25344914, 2014). "It was hypothesized that Rac-dependent Rho activation in response to narrow-band UVB irradiation may serve as a negative feedback to avoid exorbitant dendrite extension promoted by the activated Rac1, according to the role of RhoA activation in dendrite retraction in B16 melanoma cells." (PMID 24649261, 2013). "Chromosome 7, with frequent copy number gains in all four cancers, harbors several key oncogenes such as EGFR, CDK6, and MET in glioma; KMT2C and PMS2 in medulloblastoma; BRAF, RAC1, and TRRAP in melanoma." (PMID 41537310, 2026). "Significance: Cotargeting the MAPK and the PREX2/RAC1/PI3Kβ pathways has remarkable efficacy and outperforms monotherapy MAPK inhibition in BRAF-mutant melanoma, supporting the potential of this combination therapy for treating metastatic melanoma." (PMID 39636745, 2025). "Expressing Rac1 P29S in 451Lu cells, another BRAF V600-mutant human melanoma cell line, also promoted BRAFi-resistance that was partially dependent on PAK signaling, based on PAK inhibition by G-5555." (PMID 41109929, 2025).
melanoma (continued). "In vitro experiments have exhibited that wogonin inhibited NF‐kB, PI3K/Akt, MMP‐2, PI3K/Akt, Rac‐1, and ERK signaling pathways to reduce adhesion, actin remodeling in B16‐F10 melanoma cells, invasion, and cellular migration." (PMID 41164269, 2025). "In melanoma, activating Rac1 mutations appear not to function as primary driver mutations; however, they may cooperate with driver mutations to promote melanoma cell proliferation, tumor progression, and metastasis, resistance to targeted therapy, and worse patient outcomes." (PMID 41109929, 2025). "We have demonstrated that the RAC1-GEF PREX1 plays critical roles in melanoblast migration during early murine embryonic development, melanoma cell invasion and migration, and metastasis in a patient-relevant preclinical model of NRAS-mutant melanoma." (PMID 39636745, 2025). "In particular, the activation of small GTPases such as CDC42, RAB17, RAC1, and RAB27A, which regulate cytoskeletal dynamics, is thought to contribute to melanoma progression and metastasis." (PMID 40594379, 2025). "Cotargeting the MAPK and the PREX2/RAC1/PI3Kβ pathways has remarkable efficacy and outperforms monotherapy MAPK inhibition in BRAF-mutant melanoma, supporting the potential of this combination therapy for treating metastatic melanoma." (PMID 39636745, 2025). "Accordingly, it was recently described that active Rac1 modulates SRF/MRTF, which initiates a switch to a mesenchymal-like state characterized by therapy resistance in melanoma." (PMID 39513883, 2024). "By integrating a series of bioinformatics methods, our study identified 6 TLR-related genes (IFNAR2, RAC1, LBP, TLR2, MAPK10, CXCL9), which have the potential to serve as new indicators of melanoma progression and prognosis." (PMID 37666853, 2023). "Subsequently, employing a similar approach, we conducted a thorough analysis of the correlation between the clinical characteristics of melanoma and remaining five model genes, i.e. IFNAR2, LBP, MAPK10, RAC1, and TLR2." (PMID 37666853, 2023). "Of note, we validated the role of RAC1, an ERG, in modulating the behavior of melanoma cells and regulating the expression of programmed cell death-1 (PD-1)/programmed death-ligand 1 (PD-L1) and cytotoxic T-lymphocyte-associated antigen 4 (CTLA4) in vitro." (PMID 37217516, 2023). "The results revealed that the CSTB, GBF1, TYR, RAC1, SLC2A1 and NOTCH3-coding proteins were significantly enriched in melanoma samples, while CEBPB-coding protein had low expression in melanoma samples." (PMID 37217516, 2023). "Mouse models have shown that downregulation of Rac1/ROS downstream WAVE2 expression inhibits migration and invasion of B16 melanoma cells." (PMID 37202394, 2023). "Subsequently, based on molecular biology experiments, we validated that silencing the expression of RAC1, an ERG composed of the risk signature, could restrain the proliferation and migration, promote apoptosis, as well as increase the expression of PD-1/PD-L1 and CTLA4 in melanoma cells." (PMID 37217516, 2023). "The PI3K/Akt-Rac1-FAK-JNK pathway has been shown to be activated by basic fibroblast growth factor (BFGF), which facilitates melanoma migration." (PMID 36555781, 2022). "We shed light on this connection by showing that RAC1 and SRC critically maintain melanoma de-differentiation." (PMID 36271142, 2022). "Our data verified that circZNF609 controls RAC1 mRNA stability by binding with FMRP, thereby regulating the metastasis of melanoma." (PMID 35534866, 2022). "To test this, we enforced expression of hyperactive RAC1, RAC1P29S, in the three melanoma cell lines (SKMEL28, UACC257, PDX10) where RAC1-knockdown had little impact." (PMID 36271142, 2022).